HOXB4 (homeobox B4)
Description:
Sequence-specific transcription factor which is part of a developmental regulatory system that provides cells with specific positional identities on the anterior-posterior axis.
Synonyms: HOX2F; HOX-2.6; HOX2
Tractability: PROTAC: ubiquitination databases record sites on it.
Gene: Protein-coding gene on chromosome 17 (48,575,507 to 48,578,350, reverse strand). Ensembl gene ENSG00000182742.
Subcellular location: Nucleus
Subcellular location (Human Protein Atlas): Nucleoplasm; Centrosome
Pathways (Reactome):
Developmental Biology: Activation of anterior HOX genes in hindbrain development during early embryogenesis; Formation of the nephric duct
Gene Ontology:
Molecular function: sequence-specific double-stranded DNA binding; DNA-binding transcription factor activity, RNA polymerase II-specific; RNA polymerase II cis-regulatory region sequence-specific DNA binding; DNA binding; DNA-binding transcription factor activity
Biological process: hematopoietic stem cell differentiation; positive regulation of stem cell differentiation; positive regulation of transcription by RNA polymerase II; anterior/posterior pattern specification; embryonic skeletal system morphogenesis; regulation of DNA-templated transcription
Cellular component: nucleoplasm; chromatin; nucleus
Genetic constraint (gnomAD): Loss-of-function variants: 13 observed, 17.57 expected, observed/expected ratio (o/e) 0.74, 90% interval 0.48 to 1.18. The upper end of that interval is the gene's LOEUF score, 1.18, which puts it in group 5 of 6, group 1 being the genes least tolerant of losing a copy. Missense variants: 278 observed, 277.04 expected, observed/expected ratio (o/e) 1, 90% interval 0.91 to 1.11. Synonymous variants: 144 observed, 118.41 expected, observed/expected ratio (o/e) 1.22, 90% interval 1.06 to 1.4.
Homologues: Orthologues: chimpanzee HOXB4 (99% identical), macaque HOXB4 (99% identical), dog HOXB4 (98% identical), pig HOXB4 (97% identical), mouse Hoxb4 (96% identical), rat Hoxb4 (95% identical), zebrafish hoxb4a (63% identical), tropical clawed frog hoxb4 (51% identical). Paralogues in human: HOXA4 (54% identical), HOXC4 (53% identical), HOXD4 (52% identical), HOXA5 (39% identical), HOXB5 (35% identical), HOXC5 (32% identical), HOXB6 (31% identical), HOXA3 (29% identical), HOXA7 (29% identical), HOXB7 (29% identical), HOXA6 (29% identical), HOXD3 (29% identical), and 30 more.
Diseases named in the same sentence as HOXB4 in open-access papers:
HOXB4 is named in the same sentence as 48 diseases in open-access papers, as found by Europe PMC text mining. Sharing a sentence is not in itself a finding about the gene and the disease. The quoted sentences say what the papers report.
leukemia (12 papers, 2008 to 2025). A malignant (clonal) hematologic disorder, involving hematopoietic stem cells and characterized by the presence of primitive or atypical myeloid or lymphoid cells in the bone marrow and the blood. "HOXB4 is associated with the prognosis of ovarian cancer patients, leukemia resistance, and renal cancer." (PMID 33914773, 2021). "HOXB4 has been implicated as a tumor-related gene in many cancer entities, including leukemia where it is also related to poor prognosis and chemoresistance." (PMID 31717802, 2019). "Downregulation of Prdm16 might be involved in preventing leukemia in HOXB4 overexpressing LT/ST-HSCs transplanted mice." (PMID 35406494, 2022). ",112,114, 115, 116, 117,168 IGF2BP1 promotes the self-renewal and initiation of leukemia stem cells as well as the sensitivity of leukemia cells to the alkylating agents by regulating the expression of ALDH1A1, HOXB4, and MYB." (PMID 40584294, 2025). "In leukemia, IGF2BP1 increases the stemness of leukemia cells by positively regulating the hematopoietic stem cell regulators HOXB4 and MYB, as well as the stem cell marker ALDH1A1." (PMID 38328550, 2024). "Notably, several essential genes involved in HSC self-renewal, metabolism, and leukemia development were increased, including GATA2, MSI2, MYCN, CD44, GAS2, HOXB4, and HOXB6." (PMID 38216972, 2024). "Hoxb4, a 3′-located Hox gene, enhances hematopoietic stem cell (HSC) activity, while a subset of 5′-located Hox genes is involved in hematopoiesis and leukemogenesis, and some of them are common translocation partners for Nucleoporin 98 (Nup98) in patients with leukemia." (PMID 23326393, 2013). "Leukemias and clonal dominance in both animal models and human gene therapy clinical trials have been previously linked to insertional activation of LMO2, the MDS1/EVI1 gene complex, HOXB4, and a number of other transcription factor genes, but not previously to activation of an anti-apoptotic gene." (PMID 23118966, 2012). "Both approaches (HOXB4/Pbx1 KO and NUP98-HOXB4) reconstituted myeloid and lymphoid populations in vivo without inducing leukemia." (PMID 35406494, 2022). "The latency of the disease was not significantly different between E2A-PBX1/CD3ε−/− and HOXB4/E2A-PBX1/CD3ε−/− mice, but the authors detected a higher number of leukaemia-initiating cells upon HOXB4 expression." (PMID 28819864, 2018).
ovarian carcinoma (10 papers, 2011 to 2025). A malignant neoplasm originating from the surface ovarian epithelium. "A previous report has shown that elevated HOXB4 expression facilitates the ovarian cancer progression via DHDDS." (PMID 35211403, 2022). "It has been reported that HOXB4 participates in the advancement of ovarian cancer, as well as lung, prostate, and breast cancer." (PMID 35211403, 2022). "Other studies also revealed that HOXB4 was upregulated in ovarian cancer cells and drug-resistant cells." (PMID 33479226, 2021). "In ovarian cancer, the expression of HOXB4 was closely related to poor prognosis and transcriptionally activated DHDDS to stimulate the proliferation and invasion of tumor cells." (PMID 33479226, 2021). "In the invasion assay, high expression of HOXB4 promoted the invasive capacity of ovarian cancer cells." (PMID 32178630, 2020). "HOX genes showing markedly higher expression in ovarian cancer cell lines and cancer tissue specimens compared to the normal ovaries also have the potential of acting as prognostic markers, these include HOXB4 and HOXB7." (PMID 21906307, 2011). "The high expression of HOXB4 is positively correlated with poor prognosis of ovarian cancer." (PMID 35211403, 2022). "These imply that the gain of HOXB4 or HOXB8 binding to rs9311399 may be a plausible driver that affects ovarian cancer progression and survival." (PMID 34930913, 2021). "Studies have found that HOXB4 is aberrantly expressed in ovarian cancer tissues and cell lines, compared with normal ovaries, while HOXB8 is associated with shorter survival in several independent ovarian cancer follow-up studies." (PMID 34930913, 2021). "Some studies have revealed that HOXB4 reduces the cytotoxic effect of paclitaxel and cisplatin by up-regulating ABC transporters in ovarian cancer cells." (PMID 35211403, 2022). "Many studies have found that HOXB cluster members are involved in the tumorigenesis or progression of ovarian cancer, including HOXB2, HOXB3, HOXB4, HOXB7, and HOXB8." (PMID 33815481, 2021). "However, how HOXB4 promotes ovarian cancer (OV) progression remains unclear." (PMID 32178630, 2020). "For example, Module 37 includes four HOX family genes (HOXB2, HOXB4, HOXB6 and HOXB7) that all have been extensively reported to be related with ovarian cancer." (PMID 22863767, 2012). "Down-regulation of HOXB4 enhanced the cytotoxic effects of Taxol and DDP on ovarian cancer cells." (PMID 33479226, 2021).
lung carcinoma (8 papers, 2013 to 2024). "We identified 7 DMRs corresponding to 7 differentially methylated genes (DMGs) including HOXB4, HOXA7, HOXD8, ITGA4, ZNF808, PTGER4, and B3GNTL1 that were highly associated with lung cancer by comparing the methylation profiles of lung cancer and benign nodule tissue." (PMID 37101220, 2023). "Knockdown of HOXB4 inhibited EMT-related invasion in lung cancer." (PMID 32178630, 2020). "It turned out that the expressions of B3GNTL1 and HOXD8 were significantly upregulated, while the expression of remaining five genes (HOXB4, ZNF808, ITGA4, PTGER4, and HOXA7) were significantly downregulated in lung cancer tissues (p < 0.01)." (PMID 37101220, 2023). "In addition to HOXA9, the methylation of HOXB4, HOXD8, and HOXD9 were also different between tumor and adjacent normal tissues in lung cancer." (PMID 31850197, 2019). "Although other members of the HOX gene family, such as HOXA5, HOXA10, HOXB3, HOXB4, and HOXC618,19, have been found to be overexpressed in lung cancer tissues compared with normal tissues, little is known about the expression and biological function of HOXA4 in lung cancer." (PMID 29700285, 2018). "In lung cancer, two HOX genes, HOXA7 and HOXB4, were highly methylated." (PMID 24842468, 2014). "Moreover, HOXB2, HOXB4 and HOXB7 together showed the key function in lung cancers." (PMID 23630576, 2013).
breast carcinoma (5 papers, 2009 to 2023). "However, the primary role of HOXB4 in breast cancer seems to be tumor suppression." (PMID 33479226, 2021). "Overall, CST6, HOXB4, ITIH5 and RASSF1 were more frequently methylated in CTCs from breast cancer patients compared to MNCs from healthy controls." (PMID 29190932, 2017). "HOXB4 induced EMT and contributed to breast cancer cell migration and metastasis." (PMID 32178630, 2020).
cervical carcinoma (5 papers, 2009 to 2023). A carcinoma arising from either the exocervical squamous epithelium or the endocervical glandular epithelium. "Next, both loss-of-function and gain-of-function of HOXB4 were performed in cervical cancer cell lines." (PMID 33479226, 2021). "Conversely, loss of HOXB4 promoted cervical cancer cell growth both in vitro and in vivo." (PMID 33479226, 2021). "Secondly, we conducted a series of in vitro and in vivo experiments using cervical cancer cell lines with gain or loss of function of HOXB4, and identified that HOXB4 inhibited cell proliferation and arrested the cell cycle at the transition from G0/G1 phase to S phase." (PMID 33479226, 2021). "Alternatively, HOXB4 is a transcription factor that is downregulated in cervical cancer cells and activates the Wnt/β-catenin signaling pathway." (PMID 36703136, 2023). "Lopez found that HOXB4 was only expressed in 3/11 normal cervical tissues but in the most cervical carcinoma samples (16/17) using RT-PCR25." (PMID 33479226, 2021). "The HOXB4 immunoreactivity score revealed that HOXB4 was expressed at different levels and significantly higher than that in cervical cancer." (PMID 33479226, 2021). "In the present study, we sought to investigate the role and molecular mechanism of HOXB4 in cervical cancer." (PMID 33479226, 2021). "First of all, our research demonstrated that compared with the normal cervix, HOXB4 was significantly downregulated in cervical cancer, which was inconsistent with previous studies." (PMID 33479226, 2021). "The immunohistochemical staining of cervical cancer patient samples further verified the correlation between HOXB4, β-catenin, and c-Myc." (PMID 33479226, 2021). "Consistent with our observation of in vivo experiments, IHC staining of primary tumors indicated that HOXB4 expression was negatively correlated with Ki67 in cervical cancer patients." (PMID 33479226, 2021). "Taken together, these findings suggested that HOXB4 directly transcriptional repressed β-catenin and subsequently inactivated the Wnt/β-catenin signaling pathway, leading to significant inhibition of cervical cancer cell growth and tumor formation." (PMID 33479226, 2021). "We demonstrated that HOXB4 obviously suppressed cervical cancer cell proliferation and tumorigenic potential in nude mice." (PMID 33479226, 2021). "A series of in vitro and in vivo experiments proved that HOXB4 functioned as a growth-inhibition role in cervical cancer." (PMID 33479226, 2021). "In HOXB4-overexpressed cervical cancer cells, HOXB4 was accessed to the nucleus and transcriptionally repressed β-catenin expression, leading to impaired nuclear accumulation of β-catenin, which subsequently contributed to the inhibition of tumorigenesis." (PMID 33479226, 2021). "Taken together, these data indicated that HOXB4 inhibited the growth of cervical cancer cells in vitro." (PMID 33479226, 2021). "To elucidate the role of aberrant HOXB4 expression in cervical cancer, we detected HOXB4 mRNA and protein levels in a group of cervical cancer cell lines." (PMID 33479226, 2021). "GESA analysis of the data from TCGA-CESC confirmed that HOXB4 inhibited the activity of the Wnt/β-catenin signaling pathway and correlation analysis showed that in cervical cancer, the expression of HOXB4, β-catenin, and c-myc genes were significantly negatively correlated." (PMID 33479226, 2021). "Furthermore, western blot confirmed HOXB4 was upregulated in normal cervix compared with cervical cancer." (PMID 33479226, 2021). "In summary, we found that HOXB4 was markedly downregulated in cervical cancer." (PMID 33479226, 2021). "Although recent studies have demonstrated that HOXB4 was involved in cervical cancer, its contribution to cervical cancer remains largely unknown." (PMID 33479226, 2021). "Here, we found that HOXB4 was markedly downregulated in cervical cancer." (PMID 33479226, 2021).
cervical carcinoma (continued). "To further verify whether HOXB4 inhibited cervical cancer cell growth in vitro, we performed cell counting, MTT, and colony formation experiments." (PMID 33479226, 2021). "Functional studies showed that HOXB4 had a growth-inhibition role in cervical cancer cells." (PMID 33479226, 2021). "Thus, our findings clearly proved that HOXB4 had as a tumor growth-inhibitor in cervical cancer." (PMID 33479226, 2021). "Furthermore, β-catenin re-expression rescued HOXB4-induced cervical cancer cell defects." (PMID 33479226, 2021). "Moreover, HOXB4 methylation could be a potential marker in human cervical cancer and in extrahepatic cholangiocarcinoma." (PMID 33634306, 2021). "Collectively, in cervical cancer, the absence of HOXB4 upregulated β-catenin and its downstream gene c-Myc, which contributed to the enhancement of the cell cycle and promoted tumor progression." (PMID 33479226, 2021). "To identify the potential role of HOXB4 in cervical cancer, we first performed immunohistochemistry (IHC) in 41 cases of the normal cervix (NC), 11 cases of HSIL, and 45 cases of squamous cell carcinoma (SCC), and tested the expression of HOXB4." (PMID 33479226, 2021). "Moreover, TCGA data revealed that the expression of HOXB4, β-catenin, and c-Myc showed a significant negative correlation in cervical cancer." (PMID 33479226, 2021).
acute myeloid leukemia (4 papers, 2013 to 2024). Acute myeloid leukemia (AML) is a group of neoplasms arising from precursor cells committed to the myeloid cell-line differentiation. "More surprisingly, HOXB4 was reported to correlate with acute myeloid leukemia 21, which is very consistent with our findings regarding FEZ1 expression in this disease (not published)." (PMID 29321952, 2018). "Humans possess 39 HOX genes across seven families, with specific genes like HOXB3, HOXB4, and HOXA1 to HOXA10 linked to adverse outcomes in diseases such as acute myeloid leukemia (AML)." (PMID 39200378, 2024). "Furthermore, MLL1 is required for the activation of other anterior HoxB genes but not HoxB4 in acute myeloid leukemia, and deletion of MLL1 does not affect HoxB4 transcription." (PMID 23754954, 2013).
lung adenocarcinoma (4 papers, 2009 to 2025). A carcinoma that arises from the lung and is characterized by the presence of malignant glandular epithelial cells. "Moreover, GSHR and HOXB4 were reported with differential methylations in lung adenocarcinoma." (PMID 34620221, 2021).
colorectal cancer (3 papers, 2021 to 2022). A primary or metastatic malignant neoplasm that affects the colon or rectum. "Then, we built a co-culture system to explore whether MC-LR exposure or HOXB4 upregulation to promote the macrophage infiltration of Colorectal cancer cell." (PMID 35211403, 2022).
mediastinal tumours (2 papers, 2024 to 2025). "HN-PG and the suspected non-chromaffin mediastinal tumours had low expression of the chromaffin cell marker CARTPT24, neural transcriptional regulators (TFAP2B, TOX3, GATA3, POU4F, NEUROG2, PAX2), HOX genes (HOXA1-10, HOXB4, HOXB6-9, HOXC4-HOXC13), and the long non-coding RNA HOTAIR." (PMID 40097403, 2025). "HN-PG and the suspected non-chromaffin mediastinal tumours had low expression of the chromaffin cell marker CARTP24, neural transcriptional regulators (TFAP2B, TOX3, GATA3, POU4F, NEUROG2, PAX2), HOX genes (HOXA1–10, HOXB4, HOXB6–9, HOXC4-HOXC13), and the long non-coding RNA HOTAIR." (PMID 38978571, 2024).
myeloproliferative neoplasm (2 papers, 2018 to 2020). A clonal hematopoietic stem cell disorder, characterized by proliferation in the bone marrow of one or more of the myeloid (i.e., granulocytic, erythroid, megakaryocytic, and mast cell) lineages. "The upregulation of HOXB4 in atypical myeloproliferative neoplasms was associated with malignant cancer progression." (PMID 32178630, 2020).
prostate carcinoma (2 papers, 2021 to 2025). A carcinoma that arises from epithelial cells of the prostate gland. "In normal prostate samples, we found that the major transcription regulators of stemness genes were HOXB4, NFYB, and TFE3, which differed from those in prostate cancer." (PMID 33985534, 2021).
anencephaly (1 paper, 2019). A rare neural tube defect during pregnancy, resulting in the absence of a large portion of the brain and skull in the fetus. "In conclusion, these data identify the abnormal upregulation of HOX genes, especially HOXB4, HOXC4 and HOXD1, concomitant with decreased H3K27me3 levels in human anencephaly cases." (PMID 31856916, 2019).
aplastic anemia (1 paper, 2012). Anemia resulting from bone marrow failure (aplastic or hypoplastic bone marrow). "Our results suggested that GATA-2 directly regulates HOXB4 expression in hematopoietic stem cells, which may play an important role in the development and/or progression of aplastic anemia." (PMID 23028422, 2012). "Furthermore, we assessed GATA-2 and HOXB4 expression in CD34-positive cells from patients with aplastic anemia (n = 10) and idiopathic thrombocytopenic purpura (n = 13), and demonstrated that the expression levels of HOXB4 and GATA-2 were correlated in these populations (r = 0.6573, p<0.01)." (PMID 23028422, 2012).
Arboleda-Tham Syndrome (1 paper, 2022). "The first and second DMRs overlap regions of HOXB2, HOXB3 and HOXB4 and is hypomethylated in Arboleda-Tham Syndrome patients relative to controls." (PMID 36064314, 2022).
bladder cancer (1 paper, 2020). "Homeobox B4 (HOXB4) is an important transcription factor involved in the progression of lung, breast, prostate, and bladder cancer." (PMID 32178630, 2020).
brain cancer (1 paper, 2020). A primary or metastatic malignant neoplasm affecting the brain. "Notably, there were 6 HOX genes, namely HOXA2, HOXA4, HOXB2, HOXB3, HOXB4, and HOXC4, which changed expression only in brain cancer (either in GBM, brain lower grade glioma (LGG), or in both)." (PMID 32545894, 2020).
chronic myeloid leukemia (1 paper, 2009). "Examples include a study on chronic myeloid leukemia stem cells, which showed that HH-dependent Stat3 activation orchestrates down-regulation of Hox genes such as HoxA2 and HoxB4." (PMID 19575820, 2009).
colon adenocarcinoma (1 paper, 2022). "We find that the HOXB4 mRNA expression was significantly higher in tumor tissue of colon adenocarcinoma (COAD) (P=0.045) than in normal tissue in the TCGA." (PMID 35211403, 2022).
colorectal tumors (1 paper, 2022). "In an effort to identify the potential role of HOXB4 in CRC, we utilized the public database TCGA at first to verify the elevated expression levels of HOXB4 in colorectal tumors." (PMID 35211403, 2022).